RFPL2 (ret finger protein like 2)
Synonyms: RNF79
Tractability: Antibody: the Human Protein Atlas places it where antibodies can reach.
Gene: Protein-coding gene on chromosome 22 (32,190,435 to 32,205,073, reverse strand). Ensembl gene ENSG00000128253.
Subcellular location (Human Protein Atlas): Nuclear speckles; Plasma membrane
Gene Ontology:
Molecular function: ubiquitin protein ligase activity
Biological process: innate immune response; regulation of gene expression
Cellular component: cytoplasm
Genetic constraint (gnomAD): Loss-of-function variants: 13 observed, 17.39 expected, observed/expected ratio (o/e) 0.75, 90% interval 0.49 to 1.19. The upper end of that interval is the gene's LOEUF score, 1.19, which puts it in group 5 of 6, group 1 being the genes least tolerant of losing a copy. Missense variants: 431 observed, 470.61 expected, observed/expected ratio (o/e) 0.92, 90% interval 0.85 to 0.99. Synonymous variants: 189 observed, 178.79 expected, observed/expected ratio (o/e) 1.06, 90% interval 0.94 to 1.19.
Homologues: Orthologues: chimpanzee RFPL2 (96% identical). Paralogues in human: RFPL3 (74% identical), RFPL1 (71% identical), RFPL4A (42% identical), RFPL4AL1 (42% identical), RFPL4B (24% identical), RNF135 (14% identical), SPRYD4 (9% identical), CD86 (5% identical), RNF152 (5% identical), PDCD1LG2 (5% identical), CD274 (4% identical), CD80 (4% identical).
Diseases named in the same sentence as RFPL2 in open-access papers:
RFPL2 is named in the same sentence as 1 disease in open-access papers, as found by Europe PMC text mining. Sharing a sentence is not in itself a finding about the gene and the disease.
RFPL2 shares sentences with these, for which no sentence is quoted: cancer (1 paper).